IL6 (interleukin 6)
Diseases named in the same sentence as IL6 in open-access papers (continued):
Sharing a sentence is not in itself a finding about the gene and the disease.
systemic sclerosis (continued). "Knocking down CCN2 using siRNA reduced expression of pro-fibrotic markers (fibronectin p < 0.01, collagen type I p < 0.05, α-SMA p < 0.0001, TIMP-1 p < 0.05 and IL-6 p < 0.05) in TGF-β-treated lung fibroblasts derived from systemic sclerosis patients." (PMID 33662577, 2021). "Conversely, IL-17A acts synergistically with TGF-β to increase the expression of IL-6 in fibroblasts cultured from systemic sclerosis patients." (PMID 32365896, 2020). "IL-6 expression is constitutively higher in systemic sclerosis fibroblasts compared to fibroblasts from healthy donors." (PMID 32365896, 2020). "This points to an inflammatory gene expression signature in the skin that is reminiscent of that seen in systemic sclerosis, since IL6, CCL2, and CCL5 are elevated in the serum of patients." (PMID 31917819, 2020). "Nevertheless, specific cytokines which were detected in such low levels in AAV were significantly elevated in systemic sclerosis: IL-4, IL-6, IL-17A, and IL-22." (PMID 31286195, 2019). "However, in several pathological conditions associated with increased fibrosis, such as systemic sclerosis, IL-6 can act as a profibrotic cytokine, suggesting the increase in collagen deposition observed in CAV1−/− adipose tissue could be related to the elevated levels of IL-6." (PMID 23049990, 2012). "In in vitro experiments using peripheral blood from patients with systemic sclerosis, ibrutinib reduced the production of pro-fibrotic cytokines IL-6 and tumor necrosis factor-α, while preserving the inhibitory role of IL-10, which helps suppress the overactivation of fibrotic functions in B cells." (PMID 39280007, 2024). "Moreover, in patients with systemic sclerosis and concomitant intestinal lung disease, compared to the control group, blood monocytes were found to secrete significantly higher amounts of IL-6 after exposure to LPS." (PMID 37109064, 2023). "Targeting IL-6 in systemic sclerosis patients showed moderate clinical improvement, while selective targeting of its downstream kinases such as JAK could be a potential therapeutic approach." (PMID 34258301, 2021). "Extracellular ATP could more strongly enhance IL-6 production in systemic sclerosis fibroblasts than in normal fibroblasts, which was significantly inhibited by selective P2Y2 receptor antagonists AR-C118925XX." (PMID 34380439, 2021). "Besides, significantly higher frequency of circulating, skin, and lung infiltrating Th17 cells and higher levels of serum, skin, and lung IL-17A, TGF-β1, IL-6, and RORγt were detected in mice in a bleomycin-induced murine model of systemic sclerosis." (PMID 33672430, 2021). "Anti-IL-6 target therapy can significantly improve the symptoms of systemic sclerosis." (PMID 31970102, 2019). "For instance, in systemic sclerosis (SSc), IL6 inhibition reduces dermal thickening and downregulates fibrotic markers (e.g., α-smooth muscle actin) by suppressing the TGF-β/STAT3 axis." (PMID 41544047, 2026). "M1 macrophages stimulate an inflammatory reaction by triggering cytokines such as TNF-α and IL-6, resulting in Th1 reactivity, whereas BD patients with skin lesions conferred M1 macrophage dominance in systemic sclerosis (SSc)." (PMID 34975900, 2021). "IL-6 promotes proliferation of dermal keratinocytes, and collagen production by fibroblasts, which may contribute to the pathogenesis of diseases like psoriasis, systemic sclerosis, and thyroid eye disease." (PMID 31523783, 2019). "Subsequently, excessive IL-6 expression patterns were detected in several other autoimmune inflammatory diseases including chronic rheumatoid arthritis, juvenile idiopathic arthritis, systemic lupus erythematosus, Adamantiades-Behcet’s disease, and systemic sclerosis." (PMID 31523783, 2019). "Interleukin-6 is currently attracting significant interest as a potential therapeutic target in systemic sclerosis (SSc)." (PMID 21941555, 2011).
systemic sclerosis (continued). "In systemic sclerosis-ILD, IL-6 directly activates fibroblasts via JAK/STAT3 signaling, promoting type I collagen synthesis, myofibroblast differentiation, resistance to apoptosis, and reduced MMP-mediated collagen degradation." (PMID 41465549, 2025). "Tocilizumab, which blocks both membrane-bound and soluble IL-6 R, has demonstrated the preservation of lung function in ILD in patients with early systemic sclerosis in randomized trials and post hoc analysis." (PMID 41465549, 2025). "Increased IL6 concentrations have been detected in the serum of patients suffering from systemic scleroderma with excessive ECM production, and cell culture models of scar formation also showed increased IL6 expression." (PMID 38540185, 2024). "GDF-15 was directly involved in the production of proinflammatory cytokines and chemokines, such as IL-6 and CCL2 in bleomycin-induced mice and systemic sclerosis (SSc) patients with lung involvement." (PMID 35784345, 2022). "Targeting the IL-6/TGF-β feedback loop with pirfenidone is effective in treating IPF, and tocilizumab reduces cutaneous fibrosis in systemic sclerosis." (PMID 32365896, 2020). "Previous studies have reported that IL-6 regulates GREM1 in a model of the fibrotic condition, systemic sclerosis, and it is well-established that MM PCs upregulate IL-6 in stromal cell populations." (PMID 32756430, 2020). "Interleukin-6 (IL-6) is a pleiotropic cytokine for which preliminary data have suggested that it might contribute to systemic sclerosis (SSc)." (PMID 25059342, 2014). "Thus, the marked correlation of RE-LYMP with IL-6 levels in our SSc patients might suggest RE-LYMP as an easily accessible, reliable indicator of systemic inflammation in systemic sclerosis." (PMID 39364215, 2024). "Moreover, the knockdown of STAT4 protected the bleomycin-injected mice from the development of systemic sclerosis via reducing the T cell infiltration and the cytokine levels of tumor necrosis factor-alpha (TNF-α), IL-6, IL-2, and INF-γ." (PMID 34258301, 2021). "In systemic sclerosis (SSc), IL-22 synergistically works with TNFα to induce the expression of IL-8 and CCL2 in skin fibroblasts, while the simultaneous stimulation of TGF-β1 and IL-17A can lead to an up-regulation of IL-6 expression in fibroblasts from affected skin by nearly a hundredfold." (PMID 35967331, 2022). "In vitro studies exhibited that fibroblasts from systemic sclerosis patients express high levels of α-SMA and CAMs (αvβ3 and αvβ5 integrin) that leads to sustained activation of the TGF-β pathway, as well as proinflammatory and chemotaxis cytokines such as IL-6, TNF-α, IL-1α, IL-1β, and MCP-1." (PMID 34258301, 2021). "IL-6 is known to promote endothelial cell dysfunction and regulate leucocyte recruitment to the vascular wall; therefore, it is unsurprising that FDA approved IL-6 blockers for arthritic conditions are of interest for treating off-label inflammatory conditions such as systemic sclerosis." (PMID 33050789, 2020). "When searching for “systemic sclerosis” and cytokines in the PubMed database, TGF-β had the highest number of hits, followed by IL-6, IL-4, tumor necrosis factor (TNF)-α, platelet-derived growth factor, IL-10, IL-13, IL-1, IL-2, and IL-17 indicating cytokines are related to the pathogenesis of SSc." (PMID 34064515, 2021).
triple-negative breast carcinoma (81 papers, 2013 to 2025). An invasive breast carcinoma which is negative for expression of estrogen receptor (ER), progesterone receptor (PR), and human epidermal growth factor receptor 2 (HER2). "IL-6 and IL-8 play an essential role in breast tumorigenesis, associate with poor patient survival, and are implicated in the maintenance of breast CSCs and chemotherapy resistance, particularly in basal subtype and triple negative breast cancer." (PMID 26506421, 2016). "MIR100HG promotes the proliferation of nasopharyngeal carcinoma cells via the miR-136-5p/IL-6 axis and enhances the growth of triple-negative breast cancer cells through the miR-5590-3p/OTX1 axis." (PMID 40969769, 2025). "The pro-inflammatory cytokine IL-6 is secreted more in invasive breast cancer (triple-negative breast cancer; TNBC) than in non-invasive breast cancer and affects tumor development and metastasis." (PMID 40430040, 2025). "Thereby, IL-6 was shown to be involved in lymphangiogenesis in triple-negative breast cancer, leading to tumor growth and metastasis." (PMID 39338222, 2024). "In vitro experiments showed that the senescence-related proinflammatory cytokines IL-6 and IL-8 were important for maintaining the invasive properties of the triple-negative breast cancer cell line MDA-MB-231." (PMID 37251343, 2023). "The aggressive biological behavior of triple-negative breast cancer is inhibited through IL-6 secreted by infiltrating NK cells." (PMID 34761735, 2022). "Depending on the functional assay, Ki16425 inhibited the LPA-induced stimulation in triple-negative breast cancer and luminal A cell lines in a variable intensity and enhanced secretion of IL-8, IL-6 and TNF-alpha in MDA-MB-468 cells." (PMID 35365723, 2022). "TDO2 is expressed in tumor cells that produce sufficient intracellular kynurenine concentrations to chronically activate the AhR, and by pro-inflammatory cytokines such as IL-6 in triple-negative breast cancer." (PMID 35203450, 2022). "One of the main characteristics is the elevation in the expression of IL-6, and treatment with antibodies against IL-6 inhibits the migration induced by lapatinib, which is a drug that promotes metastasis in triple-negative breast cancer cells." (PMID 36012357, 2022). "Autocrine/paracrine activation of IL6 signaling was confirmed by evaluating STAT3 activation in four triple-negative breast cancer model systems." (PMID 31511085, 2019). "CRYβB2 overexpression in triple-negative breast cancers increases invasive cellular behaviors, tumor growth, IL6 production, immune cell chemoattraction, and the expression of metastasis-associated genes." (PMID 31511085, 2019). "Nevertheless, several lines of evidence suggest that RANTES and IL-6 also play a fundamental role in the progression of triple negative breast cancer." (PMID 29707128, 2018). "Cytokine amounts declined in the triple negative breast cancer cells in a concentration-dependent manner upon pseudopterosin treatment (at a PsA-D concentration of 30 μM: 18-fold decrease of IL-6, 12-fold reduction of IL-8 and a 26-fold decrease of MCP-1)." (PMID 28832545, 2017). "The transcription factor NFκB is a master regulator of a number of cytokines (e.g. IL-6 and IL-8) involved in stemness regulation in the triple negative breast cancer." (PMID 28270211, 2017). "The maintenance of breast CSCs and their chemoresistance particularly in the basal subtype/triple negative breast cancer is essentially attributed to the synergistic effect between IL-6 and IL-8." (PMID 28270211, 2017). "Coordinate expression and secretion of IL-6, IL-8 and GRO-α via NFκB promote tumorgenesis and are associated with poor outcome in triple negative breast cancer patients." (PMID 28270211, 2017). "Studies have shown that inhibition of IL-6 expression by shRNA in triple-negative breast cancer cells can lead to the suppression of colony formation and decreased cell survival in vitro as well as decreased tumor engraftment and growth in vivo." (PMID 26840088, 2016).
triple-negative breast carcinoma (continued). "In comparison to other breast subtypes, triple-negative breast cancer cell lines secret the highest levels of IL-6." (PMID 26840088, 2016). "Interleukin (IL)-6 is particularly and highly produced by triple-negative breast cancer (TNBC) cells, and has been considered as an important contributor to immune suppression in the TME." (PMID 24156030, 2013). "By combining the PARP inhibitor (PARPi), talazoparib, with radiation, senescence was enhanced in 4T1 and MDA-MB-231 triple-negative breast cancer cell lines (based on SA-β-gal upregulation, increased expression of CDKN1A and the senescence-associated secretory phenotype (SASP) marker, IL6)." (PMID 38002066, 2023). "Recently, Li found that increased expression of GGT1 in triple negative breast cancer caused cisplatin resistance by affecting the hepatic leukemia factor (HLF), a process that may be closely linked to IL-6 levels in the immune microenvironment." (PMID 35387129, 2022). "Additionally, it was reported that EUG synergistically increased cisplatin cytotoxicity against triple negative breast cancer through the inhibition of NF-κB signalling pathway, p50 and p65 subunits phosphorylation, and IL-6 and IL-8 downregulation." (PMID 33509300, 2021). "The authors demonstrate that STAT3/IL6 stimulation governed the DRD2-induced stem cell self-renewal in triple-negative breast cancers, while the induction of cell-cycle arrest at G1 and reduction in cell proliferation and viability were reported to be independent of DRD2." (PMID 34422720, 2021). "We were able to replicate our in vivo results in vitro, whereby chronic osteoblast treatment with the conditioned media of triple-negative breast cancer cells resulted in osteoblasts that express osteopontin, but have reduced IL-6 and alpha-SMA protein expression." (PMID 30813947, 2019). "Importantly, IL6 is one of our candidate genes capturing CSC properties in triple negative breast cancer." (PMID 31709178, 2019). "Therapeutics specifically inhibiting IL-6, IL-8 and NF-κB signaling could be a promising treatment option for obese women with triple-negative breast cancer." (PMID 29930291, 2018). "It is noteworthy that irrespective of exogenous cytokine stimulation via LPS or TNFα, pseudopterosins are able to significantly reduce endogenous release of at least two cytokines in the MDA-MB-231 triple negative breast cancer cells (IL-6 1.2-fold, IL-8 1.4-fold, MCP-1 1.4-fold)." (PMID 28832545, 2017). "In addition, CX-4945 reduced IL-6 expression in a triple negative inflammatory breast cancer patient, in a xenograft model and triple negative breast cancer cell lines." (PMID 28134850, 2017). "With limited therapy options for aggressive triple-negative breast cancer, IL-6 signaling inhibitors may offer an important new therapeutic option." (PMID 26840088, 2016). "Furthermore, another more recent study by our group indicated that long-term treatment of lapatinib in triple-negative breast cancer cells increases IL6 expression through miRNA-7-dependent activation of Raf-1 signaling." (PMID 27694691, 2016). "A recent study reported that the expression levels of IL6 and IL8 in triple-negative breast cancer (TNBC) were associated with cell survival, and that the inhibition of IL6/IL8 signaling was a therapeutic strategy for improving the prognosis of patients with TNBC." (PMID 25824986, 2015). "In basal-like/triple negative breast cancer cells, β-catenin maintains the stability of epidermal growth factor receptor (EGFR)-governed genes, including interleukin-6 (IL-6)." (PMID 40562819, 2025). "Tumor cell-secreted IL6 has been reported to induce CCL5 expression in lymphatic endothelial cells and accelerate metastasis in triple-negative breast cancer." (PMID 39996058, 2025). "In triple-negative breast cancer, G protein-coupled estrogen receptor (GPER) inhibits cell invasion and angiogenesis by suppressing NF-κB/IL-6 signaling." (PMID 35292057, 2022).
triple-negative breast carcinoma (continued). "This research showed that phenylmethimazole significantly inhibited interleukin 6 (IL-6) expression by MDA-MB-231 and other triple-negative breast cancer (TNBC) cell lines." (PMID 34832940, 2021). "In triple-negative breast cancer (TNBC), cancer cell-derived IL-6 have been reported to stimulate the polarization of macrophages toward M2 phenotype, and thus promotes epithelial-mesenchymal transition (EMT) and invasion of TNBC cells." (PMID 34650968, 2021). "It has been observed that GPER activation reduces TNFα-induced IL-6 expression in the SKBR3 cell line and reduces IL-6 and VEGF-A levels in triple-negative breast cancer cell lines MDA-MB-231 and BT-549 through inhibition of NF-κB transcriptional activity." (PMID 32973677, 2020). "IL-6-mediated expression of pSTAT3, PI3K, and pAkt is high during the proliferation of triple-negative breast cancer cells." (PMID 31252615, 2019). "The activation of this pathway further triggers the non-classical NF-κB signaling pathway, leading to the release of IL-6 and activating the IL-6/STAT3 signaling pathway, ultimately promoting the survival and development of drug resistance of triple-negative breast cancer cells." (PMID 40567603, 2025). "Tocilizumab, for instance, blocks IL6/STAT3 signaling and reduces the cancer/inflammation epigenetic IL6/STAT3/NF-kB positive feedback loop, which is of immense therapeutic utility for patients with resistant triple-negative breast cancer." (PMID 36672697, 2023). "A significant increase in IL-6 expression in patients with HER-2(+) and triple-negative breast cancer may indicate a poor prognosis." (PMID 36531035, 2022). "Consistent with our findings, Fu and Lin reported that inhibiting IL-6 and IL-8 signaling using novel drug combinations (e.g., bazedoxifene/reparixin, bazedoxifene/SCH527123) achieved more effective treatment of triple-negative breast cancer and pancreatic ductal adenocarcinoma." (PMID 34063134, 2021). "We, thus, hypothesize that the CXCR2/IL6 axis plays a synergistic role with FA2H in breast CSC signaling and, possibly and in particular, among triple negative breast cancers." (PMID 31709178, 2019). "Furthermore, the triple negative breast cancer cell line MDA-MB-231 induced expression of IL-6, TNFα and MCP-1 in the presence of stimulated THP-CM (IL-6 induction 177-fold, TNFα induction nearly 10-fold and MCP-1 induction nearly 19-fold)." (PMID 28832545, 2017). "Additionally, in cell lines and in murine models of triple-negative breast cancer (TNBC), it has been observed that the activation of GPER by its G-1 agonist significantly inhibits the expression of IL-6 and VEGF-A and is also capable of suppressing the angiogenesis and progression of TNBC." (PMID 32973677, 2020). "miR-483-5p has also been found to have a carcinogenic role in triple-negative breast cancer in that it inhibits SCOS3 (suppressor of cytokine signaling 3) gene expression that may trigger the pathway of STAT3, NF-κB, and primary inflammatory cytokines such as TNF-α, IL-6, MCP-1, and IL-1β." (PMID 37298699, 2023). "As expected, the proliferation of triple-negative breast cancer cells MDA-MB-231 was not affected by E2, but IL-6 stimulated it." (PMID 39201674, 2024).